CLVS1 (clavesin 1)
Description:
Required for normal morphology of late endosomes and/or lysosomes in neurons (By similarity). Binds phosphatidylinositol 3,5-bisphosphate (PtdIns(3,5)P2).
Synonyms: CRALBPL; RLBP1L1; MGC34646; C6orf212L
Tractability: Antibody: UniProt places it where antibodies can reach, with high confidence. PROTAC: its protein half-life has been measured.
Gene: Protein-coding gene on chromosome 8 (61,057,158 to 61,501,645, forward strand). Ensembl gene ENSG00000177182.
Subcellular location: Golgi apparatus, trans-Golgi network membrane; Cytoplasmic vesicle, clathrin-coated vesicle; Early endosome membrane
Pathways (Reactome):
Vesicle-mediated transport: Lysosome Vesicle Biogenesis
Gene Ontology:
Molecular function: phosphatidylinositol-3,5-bisphosphate binding; protein binding; phosphatidylinositol bisphosphate binding
Biological process: lysosome organization
Cellular component: endosome; clathrin-coated vesicle; trans-Golgi network; trans-Golgi network membrane; early endosome membrane; Golgi apparatus
Genetic constraint (gnomAD): Loss-of-function variants: 8 observed, 30.51 expected, observed/expected ratio (o/e) 0.26, 90% interval 0.15 to 0.47. The upper end of that interval is the gene's LOEUF score, 0.47, which puts it in group 2 of 6, group 1 being the genes least tolerant of losing a copy. Missense variants: 332 observed, 444.65 expected, observed/expected ratio (o/e) 0.75, 90% interval 0.68 to 0.82. Synonymous variants: 161 observed, 172.26 expected, observed/expected ratio (o/e) 0.93, 90% interval 0.82 to 1.07.
Homologues: Orthologues: chimpanzee CLVS1 (100% identical), macaque CLVS1 (99% identical), dog CLVS1 (99% identical), guinea pig CLVS1 (98% identical), pig CLVS1 (98% identical), rabbit CLVS1 (98% identical), mouse Clvs1 (97% identical), rat Clvs1 (97% identical), tropical clawed frog clvs1 (79% identical), Drosophila melanogaster CG33966 (23% identical), Drosophila melanogaster CG30339 (22% identical), Drosophila melanogaster CG12926 (21% identical), and 9 more. Paralogues in human: CLVS2 (75% identical), RLBP1 (31% identical), TTPAL (31% identical).
Diseases named in the same sentence as CLVS1 in open-access papers:
CLVS1 is named in the same sentence as 7 diseases in open-access papers, as found by Europe PMC text mining. Sharing a sentence is not in itself a finding about the gene and the disease. The quoted sentences say what the papers report.
nephrotic syndrome (2 papers, 2022 to 2024). A collection of symptoms that include severe edema, proteinuria, and hypoalbuminemia; it is indicative of renal dysfunction. "However, a recent study found a potentially causative mutation in clavesin-1 in a case of familial childhood steroid-sensitive nephrotic syndrome." (PMID 38344712, 2024).
Duane retraction syndrome (1 paper, 2015). Duane retraction syndrome (DRS) is a congenital form of strabismus characterized by horizontal eye movement limitation, globe retraction and palpebral fissure narrowing in attempted adduction. "CLVS1 (Clavesin 1) is a Protein Coding gene; diseases associated with CLVS1 include Duane Retraction syndrome." (PMID 26334530, 2015).
autosomal recessive disease (1 paper, 2022). Autosomal recessive form of disease. "Heterozygous H310Y-KI podocytes displayed similar levels of apoptosis compared to controls, providing additional evidence for the role of CLVS1 in the development of autosomal-recessive disease." (PMID 34874915, 2022).
CLVS1 also shares sentences with these, for which no sentence is quoted: amyotrophic lateral sclerosis (1 paper); cancer (1); lung carcinoma (1); tumor (1).